GOLGA8IP (golgin A8 family member I, pseudogene)
Description:
May be involved in maintaining Golgi structure.
Synonyms: FLJ35785; formerly GOLGA9P; GOLGA8I
Gene: Transcribed unprocessed pseudogene on chromosome 15 (22,607,540 to 22,617,756, reverse strand). Ensembl gene ENSG00000277561.
Subcellular location: Golgi apparatus, Golgi stack membrane